UBE2O (ubiquitin conjugating enzyme E2 O)
Synonyms: E2-230K
Tractability: PROTAC: UniProt records ubiquitination sites on it; ubiquitination databases record sites on it; its protein half-life has been measured.
Gene: Protein-coding gene on chromosome 17 (76,389,456 to 76,453,208, reverse strand). Ensembl gene ENSG00000175931.
Pathways (Reactome):
Immune System: Antigen processing: Ubiquitination & Proteasome degradation
Gene Ontology:
Molecular function: protein binding; RNA binding; ubiquitin conjugating enzyme activity; ubiquitin protein ligase activity; ubiquitin-protein transferase activity
Biological process: positive regulation of BMP signaling pathway; protein K63-linked ubiquitination; protein monoubiquitination; retrograde transport, endosome to Golgi; protein ubiquitination
Cellular component: cytoplasm; nuclear body; nucleoplasm; nucleus; cytosol
Genetic constraint (gnomAD): Loss-of-function variants: 15 observed, 119.74 expected, observed/expected ratio (o/e) 0.13, 90% interval 0.083 to 0.19. The upper end of that interval is the gene's LOEUF score, 0.19, which puts it in group 1 of 6, group 1 being the genes least tolerant of losing a copy. Missense variants: 1,227 observed, 1,663.8 expected, observed/expected ratio (o/e) 0.74, 90% interval 0.7 to 0.77. Synonymous variants: 673 observed, 678.99 expected, observed/expected ratio (o/e) 0.99, 90% interval 0.93 to 1.06.
Homologues: Orthologues: macaque UBE2O (99% identical), chimpanzee UBE2O (96% identical), guinea pig UBE2O (95% identical), pig UBE2O (95% identical), rat Ube2o (94% identical), rabbit UBE2O (94% identical), mouse Ube2o (94% identical), tropical clawed frog UBE2O (67% identical), zebrafish UBE2O (45% identical). Paralogues in human: UBE2Z (9% identical), UBE2S (5% identical), UBE2R2 (4% identical), CDC34 (4% identical), UBE2K (4% identical), UBE2T (4% identical), UBE2B (4% identical), UBE2A (4% identical), UBE2C (4% identical), UBE2N (3% identical), AKTIP (3% identical), UBE2J1 (3% identical), and 12 more.
Diseases named in the same sentence as UBE2O in open-access papers:
UBE2O is named in the same sentence as 48 diseases in open-access papers, as found by Europe PMC text mining. Sharing a sentence is not in itself a finding about the gene and the disease. The quoted sentences say what the papers report.
breast cancer (21 papers, 2020 to 2025). A primary or metastatic malignant neoplasm involving the breast. "Breast cancer cells deficient in UBE2O show reduced glycolytic metabolites (such as glucose-6-phosphate and fructose-6-phosphate), smaller cell size, and impaired purine/amino acid biosynthesis—key processes that support rapid proliferation." (PMID 40426910, 2025). "In terms of clinical significance, data from The Cancer Genome Atlas (TCGA) show that UBE2O is overexpressed in approximately 20% of breast cancers, which is associated with the amplification of 17q25." (PMID 40426910, 2025). "Although other members of the UBE2 family have been implicated for their role in cancer metastasis, the UBE2O‐AMPKα2 axis, for example, was found to promote breast cancer metastasis." (PMID 35615976, 2022). "Additionally, patients with high UBE2O expression tend to have a higher risk of metastasis and poor prognosis in breast cancer." (PMID 37373211, 2023). "The overexpression of UBE2O in breast cancer cells significantly promoted the proliferation, epithelial-mesenchymal transition (EMT) and acquisition of stem cell characteristics." (PMID 36677797, 2023). "A gene belonging to the same family (UBE2O) has been shown to promote the proliferation, epithelial–mesenchymal transformation and stemness properties of breast cancer cells through the UBE2O/AMPKα2/mTORC1-MYC positive feedback loop." (PMID 35681547, 2022). "UBE2O ablation in MMTV-PyVT mice markedly inhibits breast cancer initiation, progression, angiogenesis and lung metastasis." (PMID 37533513, 2022). "HCG18 by miR-103a-3p binding positively regulates the expression UBE2O (ubiquitin conjugating enzyme E2O) and thus activates the UBE2O/mTORC1 axis in breast cancer cells." (PMID 36139678, 2022). "UBE2O inhibits myeloma tumor growth, while it promotes tumorigenesis in breast cancer and prostate cancer by degradation of AMPKα2 and facilitated lung cancer progression by degradation of Mix1." (PMID 36443833, 2022). "In human breast cancer, tumor tissue microarrays (TMAs) presented a high expression of UBE2O staining." (PMID 34451875, 2021). "The overexpression of UBE2O is confirmed in breast cancer tissues, and UBE2O expression is higher in patients with a poor prognosis and an increased risk of metastasis." (PMID 34790050, 2021). "It has been documented that UBE2O is frequently amplified or overexpressed in several types of human cancer, which include bladder cancer, breast cancer, and liver cancer." (PMID 32901121, 2021). "UBE2O expression is amplified and relates to AMPKa2/mTOR/HIF1a in human cancers, using the existing microarray database: Liu’s BCa, breast carcinoma (GEO: GSE22820, n = 176); Stephenson’s CaP, prostate carcinoma (n = 97); Taylor’s CaP (GEO: GSE21032, n = 179)." (PMID 34451875, 2021). "UBE2O promotes the proliferation, epithelial-mesenchymal transformation, and stemness properties of breast cancer cells through the UBE2O/AMPKα2/mTORC1 positive feedback loop, and UBE2O facilitates tumorigenesis and radioresistance by promoting Mxi1 ubiquitination and degradation." (PMID 35668470, 2022). "Alterations in UBE2O expression were observed in various types of cancer, including prostate cancer, breast cancer, and head and neck squamous carcinoma, suggesting that UBE2O may be an oncogene." (PMID 34199813, 2021). "The targeted depletion of UBE2O resulted in a remarkably delayed onset of prostate and breast tumors and impairment in invasion and distant metastasis in mouse models of prostate and breast cancer." (PMID 34199813, 2021). "In breast cancer cells, UBE2O up-regulates MYC through the AMPKα2/mTORC1 axis." (PMID 33081056, 2020). "Other researchers also have shown that AMPKα2 is ubiquitinated by ubiquitin-conjugating enzyme E2O (UBE2O) in a mouse model of breast cancer, which activates the mammalian target of rapamycin-hypoxia inducible factor 1-α (mTOR-HIF1-α) pathway and triggers cancer growth." (PMID 32185076, 2020).
breast cancer (continued). "However, the expression profile and functional biology of UBE2O in human breast cancer (BC) remain unclear." (PMID 31907353, 2020). "In breast cancer, UBE2O promoted EMT through the UBE2O/AMPKα2/mTORC1 axis, but the relationship between UBE2O and NAP1L1 and EMT in HCC has not been studied." (PMID 38816735, 2024). "Among the 4 candidate proteins, UBE2O has been proved to bind to NAP1L1 and promote EMT in head and neck squamous cell carcinoma and breast cancer, but the relationship between UBE2O and NAP1L1 and EMT in HCC has not been studied." (PMID 38816735, 2024). "Overexpressed ubiquitin-conjugating enzyme E2O (UBE2O) in human cancer induces the ubiquitination of AMPKα2 at K470, which further promotes breast cancer progression and metabolic reprogramming." (PMID 36677797, 2023). "UBE2O promotes the proliferation, EMT, and stemness properties of breast cancer cells through the UBE2O/AMPKalpha2/mTORC1-MYC positive feedback loop." (PMID 36185617, 2022). "Another recent study demonstrates the relationship between MYC and the oncoprotein UBE2O, a protein known to promote EMT in breast cancer cells." (PMID 33081056, 2020). "However, the precise role of UBE2O in human breast cancer (BC) remains unclear." (PMID 31907353, 2020). "In addition, UBE2O also enhances epithelial–mesenchymal transition (EMT) and cancer stem cell (CSC) characteristics in breast cancer, which are crucial for invasion, metastasis, and tumor recurrence." (PMID 40426910, 2025). "UBE2O, an E2 ubiquitin-conjugating enzyme, plays a tumor-promoting role in multiple solid tumors, including breast cancer, prostate cancer, hepatocellular carcinoma (HCC), and non-small cell lung cancer (NSCLC), by driving tumor progression." (PMID 40426910, 2025).
lung carcinoma (12 papers, 2021 to 2025). "The high expression of UBE2O was associated with shorter overall survival in lung cancer patients (P < 0.05)." (PMID 32901121, 2021). "Since UBE2O controls the accumulation of Mxi1, we next investigated whether UBE2O is associated with radiosensitivity of lung cancer." (PMID 32901121, 2021). "In lung cancer, UBE2O enhances tumor radioresistance by degrading Mxi1 and is associated with poor prognosis." (PMID 40426910, 2025). "Immunohistochemistry revealed an inverse correlation between UBE2O (high) and Mxi1 (low) expression in lung cancer tissues, consolidating their functional antagonism." (PMID 40426910, 2025). "Consistently, UBE2O overexpression promotes lung cancer proliferation and radioresistance and predicts poor-prognosis patients through the negative regulation of Mxi1." (PMID 39272922, 2024). "In lung cancer, which is the deadliest malignancy worldwide, UBE2O has been shown to play a putative essential role in radioresistance." (PMID 39272922, 2024). "UBE2O targets Mxi1 for ubiquitination and degradation to promote lung cancer progression and radioresistance." (PMID 36185617, 2022). "Previous studies have found that the repression of ubiquitin-conjugating enzyme E2O (UBE2O) or aurora kinase A (AURKA) can also promote radiation-induced DNA damage in lung cancer cells." (PMID 36139006, 2022). "We also found that genetical and pharmacological inhibition of UBE2O impair tumorigenesis and radioresistance in a Mxi1-dependent manner in lung cancer." (PMID 32901121, 2021). "Collectively, our results indicate that UBE2O promotes cell proliferation and radioresistance via its ability to degrade Mxi1 in lung cancer cells." (PMID 32901121, 2021). "Collectively, our work reveals that UBE2O facilitates tumorigenesis and radioresistance by promoting Mxi1 ubiquitination and degradation, suggesting that UBE2O is an attractive radiosensitization target for the treatment of lung cancer." (PMID 32901121, 2021). "Our clinical data clearly show that UBE2O protein is overproduced and inversely correlated with Mxi1 expression in lung cancer." (PMID 32901121, 2021). "Functionally, genetical or pharmacological inhibition of UBE2O significantly impairs lung cancer progression and radioresistance in vitro and in vivo." (PMID 32901121, 2021). "In this study, we demonstrate that UBE2O targets Mxi1 for ubiquitination and degradation, which is a new mechanism for Mxi1 regulation in lung cancer." (PMID 32901121, 2021). "UBE2O protein levels were upregulated in five lung cancer cell lines compared with that in normal human epithelial cell line HBE." (PMID 32901121, 2021). "The biological functions showed that UBE2O plays oncogenic roles in lung cancer and is expected to be an attractive target for anticancer and radiosensitization therapeutics." (PMID 32901121, 2021). "Mxi1 is identified as a substrate of UBE2O and mediates the tumor-promoting role of UBE2O in lung cancer." (PMID 34790050, 2021). "Consistent with the neutral comet assay, DNA damage-induced Rad51 foci formation was drastically decreased when UBE2O was knocked down, indicating that loss of UEB2O can accelerate DNA damage and impair DNA repair in lung cancer." (PMID 32901121, 2021). "Clinically, UBE2O is remarkedly upregulated and negatively correlated with Mxi1 downregulation in lung cancer tissues." (PMID 32901121, 2021). "Collectively, these results suggest that UBE2O depletion impairs tumorigenesis and enhances the radiosensitivity in lung cancer in vitro and in vivo." (PMID 32901121, 2021). "Elevated UBE2O expression accelerates lung cancer cell proliferation and tumor growth." (PMID 40426910, 2025). "Endogenous UBE2O bound Mxi1 in two lung cancer cell lines (H1299, A549)." (PMID 40426910, 2025). "Furthermore, the in silico analysis of the TCGA database demonstrated that UBE2O amplification is frequently found in many types of gastric and lung cancers." (PMID 39272922, 2024).
lung carcinoma (continued). "Recent studies showed that UBE2O is amplified in several human cancers including liver, beast, bladder and lung carcinoma, indicating UBE2O may exert a positive effect on cancer cell survival." (PMID 37533513, 2022). "Considering that UBE2O negatively controls the abundance of Mxi1 at translational level, our results strongly suggest that UBE2O overexpression may result in the downregulation of Mxi1 in lung cancer." (PMID 32901121, 2021). "Moreover, genetical and pharmacological inhibition of UBE2O impairs tumorigenesis and radioresistance in a Mxi1-dependent manner in lung cancer in vitro and in vivo." (PMID 32901121, 2021). "UBE2O depletion overcomes lung cancer radioresistance in vitro and in vivo, indicating that UBE2O may be an attractive radiosensitization target in lung cancer." (PMID 32901121, 2021). "Furthermore, our rescue experiments showed that the inhibiting effects of UBE2O depletion on the proliferation and radioresistance of lung cancer cells can be restored by Mxi1 knockdown." (PMID 32901121, 2021). "Given that UBE2O depletion enhanced the radiosensitivity of lung cancer, we therefore wondered whether pharmacological inhibition of UBE2O with ATO had a similar effect." (PMID 32901121, 2021). "To determine the roles of UBE2O in lung cancer progression, we performed cell growth and proliferation assays and showed that UBE2O silencing with two different specific siRNAs led to a greater inhibition of cell growth and colony formation ability in A549 and H1299 cells." (PMID 32901121, 2021). "To confirm whether UBE2O is indeed upregulated in lung cancer, we validated the specificity of anti-UBE2O antibody and then detected the expression of UBE2O in 82 pairs of lung adenocarcinoma tissues and adjacent tissues using IHC staining." (PMID 32901121, 2021). "Given that the anticancer and radiosensitization potential of UBE2O blockade, our data provide a strong rationale that the development of UBE2O specific inhibitor may be a potential therapeutic strategy for treating lung cancer." (PMID 32901121, 2021). "Moreover, we demonstrate that UBE2O is overexpressed and negatively correlated with Mxi1 protein levels in lung cancer tissues." (PMID 32901121, 2021). "Furthermore, clonogenic survival assays revealed that UBE2O silencing enhanced the lung cancer cells radiosensitivity." (PMID 32901121, 2021). "Furthermore, we show that genetical or pharmacological blockade of UBE2O impairs tumor progression and radioresistance in lung cancer in vitro and in vivo, and these effects can be restored by Mxi1 inhibition." (PMID 32901121, 2021). "In addition, we did not observe a significant change in irradiation-induced G2/M arrest or early apoptosis in UBE2O-depleted lung cancer cells." (PMID 32901121, 2021). "Our data clearly show that UBE2O silencing inhibits lung cancer cell growth and proliferation in vitro and in vivo, suggesting that UBE2O may function as an oncoprotein that promotes lung cancer progression." (PMID 32901121, 2021). "UBE2O could mediate Mxi1 ubiquitination and then promote lung cancer progression and radioresistance." (PMID 34976998, 2021). "Taken together, these data demonstrate that UBE2O overproduction may lead to Mxi1 downregulation and predict adverse prognosis in lung cancer patients." (PMID 32901121, 2021). "Since UBE2O negatively regulates the protein levels of Mxi1, we speculated that UBE2O might be overexpressed in lung cancer." (PMID 32901121, 2021). "Since Mxi1 is a ubiquitination substrate of UBE2O, we determined whether Mxi1 is required for the functions of UBE2O in lung cancer." (PMID 32901121, 2021). "UBE2O is highly expressed in lung cancer tissues, and its overexpression predicts poor prognosis." (PMID 34790050, 2021). "Hence, the genetical or pharmacological inhibition of UBE2O could be a potential strategy for treating lung cancer." (PMID 39272922, 2024).
lung carcinoma (continued). "Furthermore, UBE2O overexpression predicts poor clinical outcomes and correlates with Mxi1 downregulation in lung cancer tissues, indicating that targeting the UBE2O/Mxi1 axis may be an attractive therapeutic strategy for treating lung cancer." (PMID 32901121, 2021). "To determine whether the expression of UBE2O is related to the clinical outcome of lung cancer patients, we divided the 82 lung cancer patients into UBE2O high and low-expression group based on the intensity of staining and the percentage of positively stained tumor cells." (PMID 32901121, 2021). "Therefore, we surmised that UBE2O might act as an oncoprotein in lung cancer." (PMID 32901121, 2021). "Notably, inactivation of UBE2O with ATO dramatically upregulated the protein levels of Mxi1 and enhanced radiosensitivity in lung cancer, suggesting that ATO exerts radiosensitization effect via the inhibition of the UBE2O-Mxi1 axis." (PMID 32901121, 2021).